DDX21 (DExD-box helicase 21)
Diseases named in the same sentence as DDX21 in open-access papers (continued):
Sharing a sentence is not in itself a finding about the gene and the disease.
tumor (29 papers, 2013 to 2026). "Shorter recurrence-free survival was associated with high DDX21 (HR: 1.961, 95% CI: 1.219–3.153, p=0.005), larger tumor size (HR: 1.825, 95% CI: 1.139–2.925, p=0.012), and advanced BCLC stage (HR: 3.676, 95% CI: 2.626–5.974, p < 0.001)." (PMID 39866844, 2025). "To assess whether DDX21 expression was also associated with tumor progression in PDAC, we collected biopsies from matched primary lesions and liver metastases of 11 patients who underwent EUS-TA for diagnostic purposes." (PMID 40002164, 2025). "To this end, we herein analyzed the characteristics of DDX21 gene expression, protein expression, immunohistochemistry, gene mutation, immune infiltration, and protein phosphorylation, and the DDX21 genes of 33 TCGA tumor types were systematically identified." (PMID 36505822, 2022). "Finally, the subcutaneous tumour formation experiment in mice confirmed that overexpression of DDX21 after knocking down TRIP13 could partially restore the inhibition of subcutaneous tumours in mice caused by knocking down TRIP13." (PMID 39187490, 2024). "Our findings demonstrate that the proper molecular ratio of U3 snoRNA/DDX21 determines mitotic cell fate, and disruption of the molecular balance between U3 snoRNA and DDX21 might provide a potential strategy for tumor therapy through interfering with the PR assembly and causing mitotic catastrophe." (PMID 38760378, 2024). "The subgroup of HCC patients with high DDX21 expression and larger tumor size showed worst overall survival and recurrence-free survival than the other subgroups." (PMID 39866844, 2025). "For instance, TRIP13 contributes to GC cell growth, movement, and penetration in a laboratory setting, along with tumor development and spread in a living organism by stabilizing DDX21 expression." (PMID 41007830, 2025). "We also found upregulation of DDX21 in HCC patients with larger tumor sizes compared to HCC patients with smaller tumor sizes." (PMID 39866844, 2025). "Coherently, the DDX21 protein was also found to be upregulated in 5% of PDAC samples from the Clinical Proteomic Tumor Analysis Consortium (CPTAC)." (PMID 40002164, 2025). "Together, our study further supports the pro-oncogenic activity of DDX21 in this highly aggressive and lethal tumor type." (PMID 40002164, 2025). "GEPIA2 was also used to study the relationship between DDX21 expression and tumor pathological stages." (PMID 36505822, 2022). "In different tumor types such as ACC, CESC, KIRP, MESO, PAAD, and BLCA, high DDX21 expression is associated with poor prognosis." (PMID 36505822, 2022). "Consistently, multivariate Cox regression analyses also further confirmed the independent prognostic values of lncRNA-ZFAS1 and DDX21 after adjusting for confounders including age and pathological pattern at diagnosis for OS and tumor stage for DFS." (PMID 33202381, 2020). "Thereafter, we enlarged the CRC patient samples to further clarify the expression association of lncRNA-ZFAS1 and DDX21, which included 157 pairs of CRC tissues and matched tumor-adjacent control tissues detected by ISH and IHC assay." (PMID 33202381, 2020). "In order to study the subcellular localization of DDX21 in both tumor tissue and tumor cell lines, indirect immunofluorescence was applied." (PMID 25260534, 2014). "Strong DDX21 staining correlated with a high rate of proliferation as detected by Ki67 on these tumor tissues." (PMID 25260534, 2014). "Together, these results point to an essential role for DDX21 in tumor cell survival, proliferation, and transformation through two independent activities: rRNA processing and c-Jun activation." (PMID 25260534, 2014). "Tumor cells expressing high levels of endogenous DDX21 undergo apoptosis after acute DDX21 knockdown, resulting in significant reduction of tumorigenicity in vitro and in vivo." (PMID 25260534, 2014). "The knockdown of DDX21 significantly inhibited tumor growth." (PMID 40301349, 2025).
tumor (continued). "Notably, the worst overall survival and recurrence-free survival were observed in HCC patients with high DDX21 expression in combination with larger tumor size, advanced BCLC stage, or poor histological grade compared with other subgroups." (PMID 39866844, 2025). "Notably, miR-218-5p was severely downregulated in AP, as well as in CRC, and found to regulate CRC via targeting key tumor-promoting genes, including Baculoviral IAP Repeat Containing 5 (BIRC5), encoding Survivin, and DExD-Box Helicase 21 (DDX21)." (PMID 40362385, 2025). "Multivariate analysis revealed that DDX21 expression (HR: 2.098, 95% CI: 1.294–3.403, p=0.003), tumor size (HR: 1.899, 95% CI: 1.184–3.047, p=0.008), and BCLC stage (HR: 2.958, 95% CI: 1.826–4.792, p < 0.001) were independent risk factors for overall survival in HCC patients." (PMID 39866844, 2025). "The tumour load of mice was substantially reduced when DDX21 was knocked down." (PMID 38572589, 2024). "As a nuclear autoantigen, DDX21 may induce DDX21-specific autoimmunity against tumor cells in MSI tumors, which could lead to better clinical outcomes for patients and potentially improve responses to immune checkpoint inhibitors." (PMID 39769343, 2024). "Previous results showed that loss of DDX21 expression suppressed the CRC cell proliferation, cell cycle and tumor growth, suggesting that DDX21 may play an important role in the tumorigenesis of CRC." (PMID 37029300, 2023). "The top 100 genes that correlated with NUDCD1 expression indicated 4 common members: FAM91A1, DCAF13, MED30 and DDX21, and their corresponding expression in different tumor types could be established." (PMID 37338527, 2023). "DDX21 was mainly expressed in the tumor nucleus and highly expressed in some mitotic cells." (PMID 37988222, 2023). "DDX21 IHC staining was mild in normal lung and endometrium tissues but high in tumor tissues." (PMID 36505822, 2022). "DDX21 staining was mild in normal colon and breast tissue samples but robust in tumor tissues." (PMID 36505822, 2022). "Additionally, the interactive effects of lncRNA-ZFAS1, DDX21 expression and the environmental factors, clinical variables were detected by unconditional logistic regression adjusted by gender, ages, tumor size and differentiation and so on." (PMID 33202381, 2020). "DDX21 was detected mostly in the tumor cell nuclei, with high expression in some mitotic cells." (PMID 33328538, 2020). "All ALK+ ALCL cases showed a strong nucleolar expression of DDX21 in the tumor cells." (PMID 23741337, 2013). "Additionally, combining DDX21 inhibition with other treatment modalities, such as immunotherapy or targeted therapies aimed at the tumor microenvironment, could enhance therapeutic efficacy." (PMID 39769343, 2024). "Furthermore, DDX21 interacted with CDC5L to exert the tumor-promoting effects in CRC." (PMID 34903139, 2021). "Our experiments confirmed that DDX21 and TRIM28 are highly expressed in CRC and demonstrated that downregulation of either gene significantly inhibits tumor cell proliferation and migration." (PMID 41194971, 2025). "In the present work, we found that DDX21 expression was positively correlated with CAF and CD8+ filtering in several tumor types, such as ACC, BRCA-LumA, CESC, COAD, GBM, HNSC (HPV+/−), KIRP, LIHC, LUAD, LUSC, MESO, OV, PAAD, and THYM." (PMID 36505822, 2022). "The role of DDX21 and CDC5L on the cell proliferation, cell cycle and tumor growth were evaluated both in vitro and in vivo." (PMID 34903139, 2021). "PARP inhibition on the other hand resulted in reduced tumor cell growth by modulating rRNA levels, DDX21 ADP-ribosylation and DDX21 localization." (PMID 32640701, 2020). "Thereafter, we detected the expression of POLR1B, and assessed possibly correlation with LncRNA-ZFAS1 or DDX21 in this included relative large samples containing 157 paired of CRC tissues and matched tumor-adjacent control tissues by TMA and IHC assays." (PMID 33202381, 2020).
tumor (continued). "DDX21, a DDX/DHX protein, is involved in tumor growth, DNA repair, and metastasis." (PMID 40301349, 2025). "Additionally, in the tumour group overexpressing DDX21 after knocking down TRIP13, the positive rates of DDX21 and Ki67 significantly recovered." (PMID 39187490, 2024). "Immunohistochemical experiments also showed that the positive rates of TRIP13, DDX21, and Ki67 were significantly reduced in the TRIP13 knockdown tumour group, while after rescuing the expression of TRIP13, the positive rates of TRIP13, DDX21, and Ki67 were significantly restored." (PMID 39187490, 2024). "Similarly, RT-PCR and qPCR method confirmed the elevated expression of lncRNA-ZFAS1 and DDX21 between 20 pairs of CRC tissues and matched adjacent-tumor controls, suggesting the possibly positive correlation of lncRNA-ZFAS1 with DDX21 in CRC cells and tissues." (PMID 33202381, 2020). "Our findings demonstrated that immunization with the Ddx21 mutant peptide (Ddx21MT), unique to KPL 160302S, could significantly increase the proportion of central memory T cells (TCM) in mice and activate anti-tumor immunity." (PMID 39981234, 2025). "Nevertheless, the role of DDX21 in different tumor types has not been thoroughly investigated." (PMID 36505822, 2022). "Our bioinformatics analysis revealed that the expression levels of DDX21 and TRIM28 in tumor tissues were elevated compared with normal tissues, and they were classified as high‐risk prognostic factors." (PMID 41194971, 2025).
infection (16 papers, 2013 to 2025). The state of being infected such as from the introduction of a foreign agent such as serum, vaccine, antigenic substance or organism. "Infection of A549 cells with dengue virus causes DDX21 to partially relocate from the nucleus to the cytoplasm." (PMID 34125604, 2021). "The protein levels of DDX21 gradually decreased in the mock-infected PK-15 cells and fell to their lowest level at 36 h post-infection (hpi)." (PMID 40006921, 2025). "The upregulation of DDX21 expression has also been observed during infections with Chum salmon reovirus in the ZF4 cell line and Spring viremia of carp virus in carp." (PMID 39769343, 2024). "The expression level of DDX21-HA decreased gradually upon SVA infection, which was consistent with the proteomics results." (PMID 35911774, 2022). "The results revealed that the expression of DDX21 decreased in SVA-infected cells with the prolongation of infection time." (PMID 35911774, 2022). "The transcription level of DDX21 was inconsistent with the translation level, implying that SVA infection affects the function of DDX21." (PMID 35911774, 2022). "The results showed that the transcriptional and translational levels are almost identical to DEPs except for DDX21 during SVA infection." (PMID 35911774, 2022). "During FMDV infection, DDX21 was degraded; furthermore, an increase in DDX21 mRNA levels was observed during infection." (PMID 34578346, 2021). "Genetic studies showed that the DDX21-TRIF signaling pathway is required for S100A9 gene expression/production during infection." (PMID 24391503, 2014). "DDX proteins (e.g. DDX21) can function as cytosolic PRR in mouse dendritic cells (mDCs) to induce type-I interferon during infection." (PMID 24391503, 2014). "In both cell lines a strong upregulation of the isoforms LAP* and LAP was detected three days after infection together with clear upregulation of DDX21." (PMID 23741337, 2013). "The efficient downregulation of DDX21 mRNA and protein in these two cell lines after the first infection produced also growth retardation; however, the effect was stronger in Mac-2A cells (94.3%) than in in Granta 519 cells (64.1%)." (PMID 23741337, 2013). "Additionally, DDX21 plays a key role in the antiviral defense of host by interacting with viral proteins to regulate essential stages of the infection process." (PMID 39769343, 2024). "However, in the later stages of infection, the viral NS protein binds to the N-terminal domain of DDX21, displacing PB1 and overcoming the inhibitory effect." (PMID 39769343, 2024). "Moreover, DDX21 facilitates redistribution to the cytoplasm to reduce IFN-β production through disrupting the DDX1-DDX21-DHX36 complex during infection." (PMID 38380105, 2024). "Although infection with SVA after treatment of cells with CQ can alleviate the degradation of DDX21, it may be related to autophagy." (PMID 35911774, 2022). "This hypothesis is further supported by our data showing that AnkG influences transcription also during infection, and that DDX21 as well as AnkG are crucial for efficient anti-apoptotic activity and CCV formation during C. burnetii infection." (PMID 35134097, 2022). "Moreover, the infection process of human cytomegalovirus, human immunodeficiency virus, and dengue virus were also regulated by DDX21." (PMID 35911774, 2022). "Our Western blot results show that DDX21 was degraded at 5, 7, 9, and 12 h post-infection (hpi)." (PMID 34578346, 2021). "Infection of cells with DENV attenuated the DDX21 signal within nuclei for all cell lines, which may be explained by the finding that DENV proteins (NS5 and capsid) shuttle to the nucleolus and likely alter its function like other viruses." (PMID 32463448, 2020). "Because of the very high DDX21 mRNA expression levels, a second infection was performed after 24 hours, which resulted in a further mRNA reduction of 92% compared to 66% after the first infection." (PMID 23741337, 2013).
infection (continued). "Thus, the SVA infection inevitably affects the protein function of DDX21." (PMID 35911774, 2022). "Our studies have thus, underscored the role of a DAMP molecule (i.e. extracellular S100A9) in regulating virus-associated inflammation and uncovered a previously unknown function of the DDX21-TRIF-S100A9-TLR4-MyD88 signaling network in regulating inflammation during infection." (PMID 24391503, 2014). "In this context, DDX21 binds to the HIV Rev protein, a key regulator of the viral life cycle, to modulate gene transcription late in infection." (PMID 39769343, 2024). "In mock-infected cells, DDX21 (red) resided in the nucleolus; however, upon FMDV (green) infection, DDX21 was translocated into the cytoplasm, where FMDV replication occurs." (PMID 34578346, 2021). "At a later time of infection, with the accumulation of virus NS1 protein, the inhibition of DDX21 was relieved in WT and mutants." (PMID 32714761, 2020). "DDX21 is antiviral against dengue virus, promoting IFN-β induction during infection; in turn, the dengue virus ns2B/3 protein complex directs the proteasomal degradation of DDX21 to counteract this signaling." (PMID 32033386, 2020). "The prevention of repression of DDX21 at the protein and mRNA levels occurred dose dependently in the PCV3-infected PK-15 cells (p < 0.05) or in the 3D4/21 cells (p < 0.05) at a multiplicity of infection (MOI) of 0.2, 1.0, and 5.0." (PMID 40006921, 2025). "Likewise, the 3’ UTRs of Ddx58, Ddx3x, Ddx21, Ifit2 and Ifit3, were significantly shorter in primary BMDMs from Cpsf6+/- mice, and such shortening was more pronounced upon VSV-eGFP infection." (PMID 38416782, 2024). "DDX21 translocates from nucleus to cytoplasm, activating the innate immune response against Dengue Virus through stimulating IFN-β induction and consequently hinders Dengue Virus replication in the early phases of infection." (PMID 35003193, 2021). "In comparison, HSV-1 only slightly cleaved DDX21, even at the late stage of infection, and the amount of full-length DDX21 was not significantly decreased." (PMID 34125604, 2021). "During infection with DENV, DDX21 relocates to the cytoplasm and promotes interferon responses." (PMID 32033386, 2020). "Here, we describe DDX50, which shares 55.6% amino acid identity with DDX21, as a non-redundant factor that promotes activation of the IRF3 signalling pathway following its stimulation with viral RNA or infection with RNA and DNA viruses." (PMID 35215908, 2022).
DDX21 also shares sentences with these, for which no sentence is quoted: thymoma (2 papers); adrenocortical carcinoma (1); benign tumors (1); cholangiocarcinoma (1); colon adenocarcinoma (1); connective tissue diseases (1); depression (1); diffuse large B-cell lymphoma (1); endocervical adenocarcinoma (1); esophageal carcinoma (1); gastrointestinal tumours (1); glioma (1); Gynecologic Cancers (1); head and neck squamous cell carcinoma (1); head and neck tumor (1); influenza (1); lung squamous cell carcinoma (1); lymphoid neoplasm (1); metastatic melanoma (1); neuropathy (1); pancreatic adenocarcinoma (1); Pancreatic Cancer (1); rectum adenocarcinoma (1); schizophrenia (1); scleroderma (1); Shwachman-Diamond syndrome (1); stomach adenocarcinoma (1).